IDO2 (indoleamine 2,3-dioxygenase 2)
Diseases named in the same sentence as IDO2 in open-access papers (continued):
Sharing a sentence is not in itself a finding about the gene and the disease.
glioma (9 papers, 2013 to 2024). A benign or malignant brain and spinal cord tumor that arises from glial cells (astrocytes, oligodendrocytes, ependymal cells). "The allelic status of IDO2 has also been evaluated in patients with glioma treated with chloroquine (CQ)." (PMID 39594642, 2024). "IDO-2 was constitutively expressed by the vast majority (approximately 80%) of glioma samples analysed." (PMID 25415278, 2014). "Regarding IDO2, there are few reports about the participation of this enzyme in gliomas." (PMID 36355137, 2022). "However, there is a recent report showing that the expression of IDO2 was positively correlated with the grades of glioma." (PMID 32296044, 2020). "In response to IFN-γ stimulation, all of glioma analysed demonstrated IDO-2 expression." (PMID 25415278, 2014). "The significant increase in constitutive IDO-2 expression in glioma cells compared to constitutive expression in HFA further corroborates this hypothesis." (PMID 25415278, 2014). "The significantly higher IDO-2 expression in IFN-γ stimulated glioma cells compared to unstimulated, may suggest that IDO-2, like IDO-1 can be potentiated by IFN-γ." (PMID 25415278, 2014). "Indoleamine-2,3-dioxygenase-2 (IDO2) can also be therapeutically targeted to catalyze the conversion of tryptophan to canine urine; this target is upregulated in gliomas and other types of cancer." (PMID 36407768, 2022). "In this study, the expression profiles of IDO1, IDO2, and TDO in paraffin-embedded tissue sections and the total activity of IDO1, IDO2, and TDO in serum samples from glioma patients at different pathologic grades were investigated." (PMID 32296044, 2020). "Immunohistochemistry staining was used to measure the expression levels of IDO1, IDO2, and TDO in paraffin-embedded tissue sections of 75 glioma tissue donors." (PMID 32296044, 2020). "Unlike gliomas, both the paraganglioma and pheochromocytoma and the neuroblastoma groups presented an increased expression of IDO2, while IDHw GBM and neuroblastomas presented a higher expression of TDO2 compared to the brain cortex." (PMID 36355137, 2022). "First, we investigated the expression of IDO1, IDO2, and TDO in different human glioma cell lines." (PMID 32296044, 2020). "Herein, by using clinical samples, we found that the expression and activity of IDO1 and/or TDO (IDO1/TDO) rather than IDO2 were positively correlated with the pathologic grades of gliomas." (PMID 32296044, 2020). "In conclusion, using clinical samples, we found that the expression and activity of IDO1/TDO rather than IDO2 contribute to the malignancy of glioma." (PMID 32296044, 2020). "Given that IDO2 expression was not correlated with the pathologic grades of glioma, it was deduced that the expression and activity of IDO1/TDO increased with the pathologic grades of glioma, and both IDO1 and TDO were involved in the malignancy of glioma." (PMID 32296044, 2020). "In this study, using paraffin-embedded tissue sections from patients with glioma (75 cases) at different pathologic grades, it was found that the expression of IDO1/TDO rather than IDO2 was positively correlated to the pathologic grades of gliomas." (PMID 32296044, 2020). "Aside from IDO1, IDO2, and TDO are also tryptophan catabolic molecules co-expressed by glioma." (PMID 23720663, 2013). "However, the roles of IDO2 and TDO in the regulation of Treg recruitment to glioma has yet to be investigated." (PMID 23720663, 2013). "Collectively, these data suggest that, in addition to IDO1, IDO2 and TDO may also be high-impact targets for investigating their contribution to modulating Treg levels, as well as overall future therapeutic possibilities for glioma patients." (PMID 23720663, 2013). "However, IDO2 expression was not correlated with the overall survival of glioma patients." (PMID 32296044, 2020).
glioma (continued). "In IDO1-, IDO2-, and TDO-expressing glioma tissue samples, it was found that the expression of IDO1 and TDO rather than IDO2 was positively correlated with the pathologic grades." (PMID 32296044, 2020).
pancreatic cancer (8 papers, 2014 to 2023). "In particular, IDO2 activity status has been genetically linked to radio-responsiveness in pancreatic cancer patients." (PMID 36032151, 2022). "Other notable genes downregulated included Ido2 (3.05-fold) (p=0.0001) which has been reported to influence tumour progression in pancreatic cancer." (PMID 36817448, 2023). "Pancreatic cancer cells have been shown to upregulate IDO2 as a means of achieving immunological tolerance via localized changes in the immune environment." (PMID 36359832, 2022). "In cancer, there are reports of IDO2 overexpression in certain gastrointestinal tumors, including frequent overexpression in pancreatic cancer." (PMID 25477879, 2014). "When it comes to pancreatic cancer, IDO2 is being looked at as a potential new biological target." (PMID 36359832, 2022). "In the same study, IDO2 was detected by immunohistochemistry in the tumor cells from 12 out of 12 pancreatic carcinoma samples, but not in normal pancreatic tissue, using an anti-IDO2 polyclonal antibody." (PMID 25691885, 2015).
depression (7 papers, 2011 to 2025). "Increased IDO1 and IDO2 are indirectly linked to reduced serotonin levels, depression, and mood disorders." (PMID 40766249, 2025). "There is a significant amount of research suggesting that elevated Ido1 and Ido2 is associated depression-like behavior and elevated Tdo2 expression is linked to Schizophrenia." (PMID 27142940, 2016). "Increased tryptophan metabolism towards the production of kynurenine via indoleamine/tryptophan-2,3-dioxygenases (DOs: Ido1, Ido2, and Tdo2) is strongly associated with the prevalence of major depressive disorder in patients and the induction of depression-like behaviors in animal models." (PMID 27142940, 2016). "Other dioxygenases with activity similar to IDO1, such as TDO2 and possibly IDO2, could play a role in increasing kynurenine levels in response to central LPS treatment to precipitate certain depression-like behaviors." (PMID 23866724, 2013). "In addition, a trend of increased KYN/TRP ratio, reflecting TRP breakdown to KYN (due to either activated IDO1, IDO2 or TDO), was found in the patients with major depression in comparison to the healthy controls (Mann–Whitney-U: 1338.0; p = 0.061)." (PMID 29109914, 2017).
breast carcinoma (6 papers, 2017 to 2025). "AhR‐mediated IDO2 expression seemingly contributes to a tumor‐promoting microenvironment in breast cancer." (PMID 41332472, 2025). "The focus of this study is to investigate the regulation of IDO2 expression in human breast cancer by AhR ligands, including environmental pollutants and endogenous ligands known to activate the AhR signaling pathway." (PMID 37408267, 2023). "In breast cancer TCGA samples, IDO2 expression increased relative to normal samples (p = 9.40 × 10−6)." (PMID 37408267, 2023). "The analysis of breast cancer datasets revealed that IDO2 expression increased in breast cancer compared with normal samples." (PMID 37408267, 2023). "In this study, the analysis of publicly available gene expression datasets revealed that IDO2 increased in various cancer types, including breast cancer, suggesting a pro-tumorigenic role for IDO2." (PMID 37408267, 2023). "Using bc-GenExMiner 4.5, IDO2 expression was assessed in the PAM50 molecular subtypes of breast cancer, in a combined dataset of 4387 samples (TCGA, SCAN-B/GSE96058, and SCAN-B/GSE81538)." (PMID 37408267, 2023). "A higher mRNA expression of IDO2 was also found in adipocyte stem cells, which are important stromal cells in the tumor microenvironment, isolated from breast cancer patients." (PMID 37408267, 2023). "In the current study, we found that toxic AhR ligands such as TCDD, BaP, and TRAP-derived PM significantly induce the expression of IDO2 in MCF-7 human breast cancer cells in an AhR-dependent manner." (PMID 37408267, 2023). "Breast cancer samples with a high proliferation index, as determined via Ki67 IHC staining, had significantly higher IDO2 expression than those with a low proliferation index." (PMID 37408267, 2023). "mRNA expression of IDO1, IDO2 and HLA-G5 in breast cancer patients were respectively 2.9, 1.6 and 2.2 fold more than normal individuals, although these differences were not statistically significant (P=0.17, 0.85 and 0.81, respectively)." (PMID 28367424, 2017). "Our findings suggest that the AhR-mediated expression of IDO2 in breast cancer could contribute to a pro-tumorigenic microenvironment in breast cancer." (PMID 37408267, 2023). "Elucidating the precise relationship between the AhR and IDO2 may shed light on novel therapeutic strategies for future breast cancer treatments." (PMID 37408267, 2023). "Basal-like breast cancer samples had the highest IDO2 expression relative to other subtypes." (PMID 37408267, 2023). "Additionally, IDO1 and IDO2 are upregulated in many tumors, including breast cancer, and the overexpression of IDO1 has been found to be associated with poor prognosis." (PMID 36765782, 2023). "Our result showed that IDO1, IDO2 and HLA-G5 had higher mRNA expressionsin ASCs isolated from breast cancer patients than those from normal individuals (P>0.05).mRNA expression of these molecules were higher in ASCs isolated from breast cancerpatients with stage III tumors than those with stage II." (PMID 28367424, 2017). "Therefore, IDO1 and IDO2 may serve as promising immunotherapeutic targets in breast cancer, as IDO inhibition can enhance antitumor immunity and thereby restore cancer immunosurveillance." (PMID 37408267, 2023). "In addition, mRNA expressions of IDO1, IDO2 and HLA-G5 in breast cancer patients with pathological stage III were respectively 2.9, 607 and 113.7 fold more than ASCs compared to stage II, however this differences were not statistically significant ( P=0.32, 0.14 and 0.17, respectively." (PMID 28367424, 2017). "Here we showed that both breast cancer andnormal ASCs can produce regulatory moleculessuch as IDO1, IDO2, and HLA-G5." (PMID 28367424, 2017). "Several studies investigated the expression of IDO1 in tumor tissue and cancer cells; however, the role and the expression of IDO2 are not well studied in breast cancer." (PMID 37408267, 2023).
breast carcinoma (continued). "Furthermore, elevated expression of IDO2 has been observed in breast cancer tissues compared with normal tissues." (PMID 41332472, 2025).
non-small cell lung carcinoma (6 papers, 2020 to 2024). A group of at least three distinct histological types of lung cancer, including non-small cell squamous cell carcinoma, adenocarcinoma, and large cell carcinoma. "Association test results of IDO2 genotypes and the risk of non-small-cell lung cancer (NSCLC)." (PMID 33968089, 2021). "In most cancers, the expression of IDO2 is upregulated, including non-small-cell lung cancer, pancreatic cancer, colon cancer, gastric cancer, and renal tumors." (PMID 36319978, 2022). "Furthermore, a significant correlation between IDO2 high expression and poor non-small cell lung cancer prognosis was detected (p = 0.011)." (PMID 32536910, 2020). "The current study reaches interesting knowledge about IDO2 in non-small cell lung cancer." (PMID 32536910, 2020). "IDO2 overexpression was documented in some human tumors, but the linkage between IDO2 expression and cancer progression is still unclear, in particular in non-small cell lung cancer (NSCLC)." (PMID 32536910, 2020). "Similar to Mandarano’s conclusion that high expression of IDO2 correlated with poor non-small-cell lung cancer prognosis, we found that there is a significant difference of RFS between IDO2-high and IDO2-low MTC patients." (PMID 36319978, 2022).
lung carcinoma (5 papers, 2020 to 2024). "Among the analyzed lung cancer histotypes, adenocarcinomas showed the highest IDO2 expression associated with high intratumoral/mixed tumor-infiltrating lymphocyte localization." (PMID 39594642, 2024). "The levels of IDO1, IDO2, and TDO proteins were evidently declined compared with those of lung carcinoma model rats (P < 0.05)." (PMID 34399782, 2021). "Compared with lung carcinoma model rats, IDO1, IDO2, and TDO protein levels in the lung tissue of normally fed rats and IDO inhibitor–intervened rats reduced evidently (P < 0.05)." (PMID 34399782, 2021). "RNAseq data for the 7 lung cancer cell lines (Minna lab, dbGaP Study Accession phs001823.v1.p1), we determined that TDO2 mRNA was elevated in A549, H1792, H2347, and H2228 cells, while IDO1 and IDO2 were low in most cell lines." (PMID 37985999, 2023).
pancreatic ductal adenocarcinoma (5 papers, 2019 to 2023). An infiltrating adenocarcinoma that arises from the epithelial cells of the pancreas. "Deletion of IDO2 has reduced the tumor volume in a mouse model of the Lewis lung carcinoma and in Krasmut pancreatic ductal adenocarcinoma." (PMID 37226257, 2023). "Interestingly, IDO2 is particularly overexpressed in pancreatic ductal adenocarcinoma (PDAC) and non-small-cell lung cancer (NSCLC)." (PMID 33968089, 2021). "Interestingly, a pro-inflammatory role of IDO2 has been recently suggested in a study evaluating the influence of IDO2 gene status in tumor progression and radiotherapy response in pancreatic ductal adenocarcinoma (PDAC)." (PMID 31134053, 2019). "Although the expression of IDO was not evaluated here, upregulation of both IDO1 and IDO2 have been shown in human pancreatic ductal adenocarcinoma and a more detailed evaluation of IDO involvement in AP is the focus of a separate, on-going study." (PMID 33925729, 2021).
cervical cancer (4 papers, 2021 to 2024). A primary or metastatic malignant neoplasm involving the cervix. "IDO2, which normally has a very restricted level of expression, has been found to be downregulated in cervical cancer compared to normal tissue." (PMID 36039641, 2022). "KIR3DL1 could serve as a relevant marker for immunosurveillance in cervical cancer cells.The immune responses of IDO2 and B cells are closely related." (PMID 39720726, 2024). "We therefore mapped the immunohistochemical distribution of the IDO1 and IDO2 proteins at the human maternal–fetal interface using a rare early pregnancy sample from a women at seven weeks of gestation who underwent hysterectomy for cervical cancer with gestational sac in utero." (PMID 38674162, 2024). "We demonstrated the obvious expression of IDO1 and IDO2, a more recently identified novel isoform of IDO, at the human maternal–fetal interface at seven weeks of gestation obtained from hysterectomy for cervical cancer with a pregnancy in situ." (PMID 38674162, 2024). "In the same study, Kyn/Trp ratio in cervical cancer tissue was correlated with IDO1 mRNA expression and not with IDO2 indicating that the increased IDO activity is due to IDO1 activity rather than IDO2." (PMID 36039641, 2022).
COVID-19 (4 papers, 2023 to 2025). A disease caused by infection with severe acute respiratory syndrome coronavirus 2. "Several studies suggest that AhR selectively induces IDO2 expression, and recent findings from COVID-19 models highlight a potential IDO2-driven positive feedback loop sustaining AhR activation in severe disease." (PMID 40471422, 2025). "IDO2 expression and activity is manifest in fatal COVID-19, PASC and even in SARS-CoV-2-infected patients who fully recovered." (PMID 37506544, 2023). "This was illustrated for example by IDO2 expression in the ependymal cells and cells in the subventricular zone of the brain in fatal/severe COVID-19,6 which are in close contact with cerebrospinal fluid that contained kynurenine." (PMID 37506544, 2023). "Rather than IDO1, our immunohistochemical analyses of lung, heart, brain and blood cells from patients with fatal/severe COVID-19 showed extensive expression and activity of the otherwise rarely expressed IDO2." (PMID 37506544, 2023). "The expression of IDO2 seems to be very high in lung tissues from patients who died with COVID-19." (PMID 39594642, 2024). "Whether IDO2 activity drives the pathology of PASC and even in fatal/severe COVID-19 needs to be established by inhibiting the IDO2-kynurenine axis." (PMID 37506544, 2023). "The abundant expression of the tryptophan-catabolizing enzyme indoleamine 2,3-dioxygenase-2 (IDO2) in fatal/severe COVID-19, led us to determine, in an exploratory observational study, whether IDO2 is expressed and active in PASC, and may correlate with pathophysiology." (PMID 37506544, 2023). "Similar to our findings in fatal COVID-19, we found that the AHR was localized in the nucleus of IDO2-positive cells, in line with the concept that AHR is driving IDO2 expression." (PMID 37506544, 2023). "Indeed, in fatal COVID-19 AHR was localized in the nucleus of IDO2-expressing cells, indicative of its transcriptional activity, and therefore likely driving IDO2 expression." (PMID 37506544, 2023). "IDO2 expression and activity in fatal/severe COVID-19, however, was in the absence of viral particles in tissue using two different antibodies against SARS-CoV-2,24 indicating that the presence of virus is not required for IDO2 expression at that stage." (PMID 37506544, 2023). "In addition, we noticed that taking tryptophan and all measured kynurenine metabolites in plasma in consideration, there is similar IDO2 activity between PASC, fatal/severe COVID-19 and Recov, although in the fatal/severe group some patients had much higher values." (PMID 37506544, 2023).